MMADHC (metabolism of cobalamin associated D)
Description:
Involved in cobalamin metabolism and trafficking. Plays a role in regulating the biosynthesis and the proportion of two coenzymes, methylcob(III)alamin (MeCbl) and 5'-deoxyadenosylcobalamin (AdoCbl). Promotes oxidation of cob(II)alamin bound to MMACHC. The processing of cobalamin in the cytosol occurs in a multiprotein complex composed of at least MMACHC, MMADHC, MTRR (methionine synthase reductase) and MTR (methionine synthase) which may contribute to shuttle safely and efficiently cobalamin towards MTR in order to produce methionine.
Synonyms: C2orf25; CL25022; cblD; HMAD; MACD; MAHCD
Tractability: Small molecule: a structure with a bound ligand is known. PROTAC: ubiquitination databases record sites on it.
Gene: Protein-coding gene on chromosome 2 (149,569,634 to 149,587,812, reverse strand). Ensembl gene ENSG00000168288.
Subcellular location: Cytoplasm; Mitochondrion
Pathways (Reactome):
Disease: Defective MMADHC causes MMAHCD
Metabolism: Cobalamin (Cbl) metabolism
Gene Ontology:
Molecular function: molecular carrier activity; protein binding
Biological process: cobalamin metabolic process
Cellular component: cytoplasm; cytosol; mitochondrion
Genetic constraint (gnomAD): Loss-of-function variants: 17 observed, 25.87 expected, observed/expected ratio (o/e) 0.66, 90% interval 0.45 to 0.99. The synonymous counts are far from expectation, so gnomAD's model fits this gene poorly and the ratio says little. Missense variants: 267 observed, 298.03 expected, observed/expected ratio (o/e) 0.9, 90% interval 0.81 to 0.99. Synonymous variants: 70 observed, 100.3 expected, observed/expected ratio (o/e) 0.7, 90% interval 0.57 to 0.85.
Gene-disease validity (ClinGen):
ClinGen rates the evidence that MMADHC causes each of these diseases.
inborn disorder of cobalamin metabolism and transport (autosomal recessive): Definitive. An inherited metabolic disease affecting cobalamin (vitamin B12) intestinal absorption, transport in the blood, uptake by peripheral cells or cellular metabolism.
Homologues: Orthologues: chimpanzee MMADHC (100% identical), macaque MMADHC (99% identical), pig MMADHC (95% identical), mouse Mmadhc (94% identical), dog MMADHC (93% identical), rabbit MMADHC (93% identical), rat Mmadhc (93% identical), guinea pig MMADHC (92% identical), tropical clawed frog mmadhc (73% identical), zebrafish mmadhcb (63% identical), zebrafish mmadhca (51% identical), Caenorhabditis elegans mmad-1 (32% identical).
Diseases named in the same sentence as MMADHC in open-access papers:
MMADHC is named in the same sentence as 17 diseases in open-access papers, as found by Europe PMC text mining. Sharing a sentence is not in itself a finding about the gene and the disease. The quoted sentences say what the papers report.
homocystinuria (14 papers, 2015 to 2025). An autosomal recessive inherited metabolic disorder caused by mutations in the CBS, MTHFR, MTR, and MTRR genes. "The MMADHC gene is associated with methylmalonic aciduria type D and homocystinuria and it is classified within the cblD complementation group." (PMID 39125597, 2024). "The cobalamin D (cblD) disorder is an autosomal recessive disease of cbl metabolism caused by mutations in the MMADHC gene that can result in isolated homocystinuria, isolated methylmalonic aciduria, or the combined form, methylmalonic aciduria and homocystinuria (MMA/HC)." (PMID 32252256, 2020). "A further search for genes revealed Methylmalonic aciduria cblD type, with homocystinuria (MMADHC) with functional relations to D110." (PMID 28604785, 2017). "Combined methymalonic aciduria and homocystinuria consists of four subtypes, MMACHC(cblC), MMADHC (cblD combined, cblD-MMA and cblD-HCY), LMBRD1(cblF) and ABCD4(cblJ)." (PMID 26149271, 2015).
cobalamin deficiency (2 papers, 2016 to 2021). "The complementation groups cblC, cblD and cblX are caused by mutations in the MMACHC (methylmalonic aciduria (cobalamin deficiency) cblC type, cblC), MMADHC (methylmalonic aciduria (cobalamin deficiency) cblD type, cblD) and the HCFC1 (host cell factor C1, cblX) genes." (PMID 27061115, 2016).
methylmalonic aciduria and homocystinuria (1 paper, 2025). An inborn error of vitamin B12 (cobalamin) metabolism characterized by megaloblastic anemia, lethargy, failure to thrive, developmental delay, intellectual deficit and seizures. "Methylmalonic aciduria and homocystinuria (MMADHC) is caused by mutations in the MMADHC gene, impairing the metabolism of vitamin B12 into its active forms, leading to the accumulation of methylmalonic acid and homocysteine." (PMID 40428338, 2025).
cancer (2 papers, 2014 to 2025). A tumor composed of atypical neoplastic, often pleomorphic cells that invade other tissues. "However, the MTR cofactor vitamin B12 (cobalamin) ATP-transporter MMADHC is overexpressed in cancer." (PMID 25243088, 2014).
MMADHC also shares sentences with these, for which no sentence is quoted: Methylmalonic aciduria (7 papers); methylmalonic acidemia (4); developmental delay (2); metabolic disease (2); adrenoleukodystrophy (1); biotinidase deficiency (1); Cognitive impairment (1); genetic disorders (1); intellectual disabilities (1); learning disabilities (1); megaloblastic anemia (1); propionic acidemia (1); Seizure (1).